ANKRD26P3 (ankyrin repeat domain 26 pseudogene 3)
Synonyms: formerly LINC00414
Gene: Transcribed unprocessed pseudogene on chromosome 13 (19,284,985 to 19,344,825, reverse strand). Ensembl gene ENSG00000237636.
Diseases named in the same sentence as ANKRD26P3 in open-access papers:
ANKRD26P3 is named in the same sentence as 1 disease in open-access papers, as found by Europe PMC text mining. Sharing a sentence is not in itself a finding about the gene and the disease. The quoted sentences say what the papers report.
osteoporosis (1 paper, 2021). A condition of reduced bone mass, with decreased cortical thickness and a decrease in the number and size of the trabeculae of cancellous bone (but normal chemical composition), resulting in increased fracture incidence. "The ANKRD26P3 gene (near LINC00421 gene) at the 13q12.11 position was associated with post-menopausal osteoporosis and large artery atherosclerosis (LAA)." (PMID 34067580, 2021).